CAT (catalase)
Diseases named in the same sentence as CAT in open-access papers (continued):
Sharing a sentence is not in itself a finding about the gene and the disease.
neuropathic pain (2 papers, 2020 to 2023). Chronic pain caused by damage to nerve fibers. "The significant decrease in antioxidant enzymes, including CAT, GPx, SOD, and TAC after BPA in this study implies that oxidative stress is one of the mechanisms of neuropathic pain." (PMID 37533160, 2023). "Their protective effects against neuropathic pain were mediated by inhibiting NOX-1, iNOS, by increasing the enzyme activity of catalase, and inhibition of inflammatory mediators, NF-κB, TNF-α, lipoxygenase, COX-2 enzymes, and PGE2." (PMID 33239680, 2020).
oligospermia (2 papers, 2021 to 2024). Decreased number of spermatozoa in the semen. "Regarding RCME, it was found that the carrot improved the semen quality of men with oligospermia via increasing the catalase level in semen, which agreed with the current findings." (PMID 34829524, 2021). "Therefore, we assessed the protein levels of SIRT1 and SIRT3, total antioxidant capacity (TAC), superoxide dismutase (SOD), malondialdehyde (MDA) and catalase activity (CAT) in the seminal plasma of 272 patients with oligospermia and 251 fertile men." (PMID 38255792, 2024).
optic neuritis (2 papers, 2007 to 2019). Optic neuritis is inflammation of the optic nerve, the nerve that carries the visual signal from the eye to the brain.The conditionmay cause sudden, reduced vision in the affected eye(s). "Our results demonstrate that most parameters of experimental optic neuritis were substantially ameliorated by genetically induced expansion of two key antioxidant enzymes, catalase and ECSOD." (PMID 17242675, 2007). "Catalase can delay demyelination in experimental optical neuritis in guinea pigs, while SOD does not appear to have any effects upon the extent of demyelination." (PMID 31262031, 2019).
oral mucositis (2 papers, 2014 to 2024). Inflammation of the mucous membranes of any of the structures in the mouth. "Also, heterozygous variants in CAT (rs7943316) displayed 0.452 (odds value) times lesser prone to experience severe oral mucositis (grade >2) with a confidence interval of 0.206–0.993 and p = 0.048." (PMID 24594932, 2014).
oral squamous cell carcinoma (2 papers, 2021). "CD59 has been evaluated as a salivary biomarker for oral squamous cell carcinomas together with M2BP, S100A9/MRP14, and catalase, achieving diagnostic sensitivity of 90%, specificity of 83%, and AUROCC of 0.93 for OSCC detection." (PMID 34359613, 2021).
prediabetes (2 papers, 2022 to 2025). "This study evaluated miR-21 and miR-30b expression alongside SOD3 and CAT plasma levels in individuals aged ≥ 65 years (n = 126) categorized into control (n = 38), prediabetes (n = 37), and T2DM (n = 51) groups." (PMID 40362367, 2025). "In the CMDs and prediabetes groups, CAT levels showed significant inverse correlations with body mass." (PMID 40362367, 2025). "In this study, we showed that the treatment of lymphocytes from patients with prediabetes and T2DM with various concentrations of T3 or H2O2 leads to a decreased activity of CAT." (PMID 36012352, 2022). "Similarly, stratification of the CMD group into prediabetes and T2DM subgroups did not reveal any differences in the plasma CAT levels between these subgroups." (PMID 40362367, 2025).
prostate adenocarcinoma (2 papers, 2020 to 2024). "At first glance, our observation that CAT levels are elevated in PCa cell lines appears to contradict findings from patient-derived prostate adenocarcinoma samples, which report reduced CAT levels and increased H2O2 levels." (PMID 39594482, 2024). "Early studies using immunohistochemical analysis consistently found lower CAT expression in prostate adenocarcinoma compared to adjacent non-malignant tissue." (PMID 39594482, 2024). "In another study, malignant epithelial cells in prostatic adenocarcinoma have been found to express lower levels of antioxidant enzymes than do benign prostatic epithelium or almost no superoxide dismutase (SOD), glutathione peroxidase (GPX), and catalase (CAT) enzyme." (PMID 32899343, 2020).
prostatic intraepithelial neoplasia (2 papers, 2012 to 2019). "Decreased CAT expression has been shown in hepatocellular carcinoma and colon, lung, kidney, and prostate cancers, as well as in precancer states, such as prostatic intraepithelial neoplasia (PIN) and cervical intraepithelial neoplasia (CIN)." (PMID 31467634, 2019).
pterygium (2 papers, 2011 to 2020). A wedge-shaped fibrovascular lesion arising from the bulbar conjunctiva and extending to the cornea. "The level of CAT was higher in women than men in the recurrent pterygium group, which coincides with an increased presence of NO in these women (data not presented)." (PMID 32908689, 2020). "Hence, the decrease of nitrosative stress probably diminishes the rate of inactivation of GSH and CAT in recurrent pterygium, thus promoting a greater level of these parameters." (PMID 32908689, 2020). "Women showed a higher level of GSH and catalase in primary pterygium, whereas a lower level of GSH and a higher level of NO in recurrent pterygium." (PMID 32908689, 2020). "The significant increase (p<0.001) in MDA, consistently accompanying significant decreases (p<0.001) in the activity of SOD, CAT, and GSH-Px in our study, leads us to think that oxidative stress is an important mechanism in the development of pterygium." (PMID 21321673, 2011).
renal dysfunction (2 papers, 2022 to 2023). "Furthermore, exercise training with treadmill running for 8 weeks increased superoxide dismutase and glutathione peroxidase activities but not catalase activity in the kidney of Nx-induced CRF rats, but exercise training did not ameliorate renal dysfunction." (PMID 36144240, 2022).
respiratory infections (2 papers, 2020). "In conclusion, catalase supplementation may represent a novel pharmacologic approach to be explored in human for prevention or treatment of respiratory infections caused by RSV." (PMID 32107411, 2020). "However, to the best of our knowledge, catalase gene polymorphisms in either the promoter or coding region have not been evaluated in the context of respiratory infections." (PMID 31947722, 2020).
rhabdomyolysis (2 papers, 2022 to 2025). Necrosis or disintegration of skeletal muscle often followed by myoglobinuria. "The catalase enzyme activity in the group treated with NS 400 mg/kg and thiol content in the NS 400 mg/kg and TQ groups were significantly higher than those of the rhabdomyolysis group (p<0.05-0.01)." (PMID 36583174, 2022). "Oral usage of RJ (100, 200, and 400 mg/kg) caused a decline in serum CPK, tissue level of total thiols, catalase activity, and renal expression of BAX compared to the rhabdomyolysis group." (PMID 40666175, 2025).
Right ventricular hypertrophy (2 papers, 2023 to 2024). In this case the right ventricle is more muscular than normal, causing a characteristic boot-shaped (coeur-en-sabot) appearance as seen on anterior- posterior chest x-rays. "Investigations were made into the right ventricular hypertrophy index (RVHI), the activities of superoxide dismutase, catalase, glutathione, and Wnt and β-catenin gene expressions in the left ventricle." (PMID 38800027, 2024).
Senile plaques (2 papers, 2023). Senile plaques are extracellular deposits of amyloid in the gray matter of the brain. "Catalase, an antioxidative enzyme, is co-localized within senile plaques and can protect cells from Aβ 1-42 toxicity." (PMID 37189641, 2023).
Sensory neuropathy (2 papers, 2024 to 2025). Peripheral neuropathy affecting the sensory nerves. "The data consistently demonstrated that HFD-induced sensory neuropathy is associated with enhanced spinal mRNA levels of superoxide dismutase (SOD), catalase (CAT), glutathione peroxidase (GPX), and nuclear factor erythroid 2-related factor 2 (NRF2)." (PMID 40298836, 2025). "Other common hits included catalase/CAT which protects neurons from oxidative stress, AZGP1, a regulator of energy metabolism, amyloid precursor-like protein 1 (APLP1), the neurotrophic amyloid precursor protein (APP) and CCT4 which was linked to sensory neuropathy." (PMID 39115595, 2024).
skin abscess (2 papers, 2012 to 2013). "Deletion of the catalase and β-toxin genes in S. aureus strains has been shown to cause strong attenuation of virulence in intramammary and subcutaneous experimental infections of ewes and lambs and in a murine skin abscess model." (PMID 22363730, 2012). "Strains of V. cambriense isolated from human cerebral and skin abscesses, intrauterine contraceptive devices, and the human vagina have been used to show that it is an anaerobic, catalase-negative, gram-positive, diphtheroid-shaped bacterium." (PMID 24451181, 2013).
Skin ulcer (2 papers, 2020 to 2024). A discontinuity of the skin exhibiting complete loss of the epidermis and often portions of the dermis and even subcutaneous fat. "Catalase might be involved in explaining the positive effects of PRF in refractory skin ulcers." (PMID 32604944, 2020).
soft tissue sarcoma (2 papers, 2011 to 2021). A malignant neoplasm arising from muscle tissue, adipose tissue, blood vessels, fibrous tissue, or other supportive tissues excluding the bones. "In contrast, bone and soft tissue sarcoma patients exhibit reduced levels of catalase and oxidative damage, which may be associated with genetic instability and early-stage tumor development." (PMID 33562681, 2021). "It was also observed that the antioxidant enzymes, SOD and CAT, were significantly reduced in patients with bone and soft tissue sarcoma (p = 0.000)." (PMID 21871117, 2011). "Enzymatic antioxidant activity of plasma catalase and SOD of bone and soft tissue sarcoma patients and healthy individuals." (PMID 21871117, 2011).
spinal cord ischemia (2 papers, 2020). Reduced blood flow to the spinal cord which is supplied by the anterior spinal artery and the paired posterior spinal arteries. "Furthermore, it has been demonstrated that there is a significant reduction of endogenous SODs and CAT levels in the anterior horn of the spinal cord following spinal cord ischemia." (PMID 31906329, 2020). "In the same way, HBOT preconditioning with a spinal cord ischemia experimental model upregulated SOD and CAT processes." (PMID 32899709, 2020).
sudden sensorineural hearing loss (2 papers, 2019 to 2020). Sensorineural hearing loss which develops suddenly over a period of hours or a few days. "In patients with sudden sensorineural hearing loss, a decrease in the CAT activity in erythrocytes was observed after the first procedure in the hyperbaric chamber, the SOD activity in erythrocytes decreased after the 14th procedure, and the GPx activity increased after the 14th procedure." (PMID 32802258, 2020).
tendinopathy (2 papers, 2024 to 2025). "Natural polyphenolic compounds, such as quercetin, possess strong antioxidative properties that might be effective against collagenase tendinopathy by inhibiting oxidative stress through the activation of SOD, CAT, and Gpx." (PMID 39997589, 2025). "In addition, DM patients have lower levels of catalase (CAT) activity, with an imbalance between oxidants and antioxidants, which increases OS to induce cell death and trigger tendinopathy." (PMID 39564114, 2024).
Thrombocytopenia (2 papers, 2008 to 2014). A reduction in the number of circulating thrombocytes. "CAT polymorphism (−330CC genotype) is significantly associated with thrombocytopenia, renal manifestations, as well as production of anti-snRNP and anti-Scl-70 antibodies in SLE patients." (PMID 24636579, 2014). "CAT polymorphism (−330CC genotype) showed a significant association with thrombocytopenia, renal manifestations, as well as production of anti-snRNP and anti-Scl-70 antibodies in SLE patients." (PMID 24636579, 2014). "Catalase is located on chromosome 11p13 where genetic linkage has been found among African-American SLE families with thrombocytopenia, a clinical manifestation associated with severe lupus in SLE affected pedigrees." (PMID 18606005, 2008).
thyroid tumor (2 papers, 2023 to 2025). A benign or malignant neoplasm affecting the thyroid gland. "Just to give a few examples, antioxidant catalase expression was found to be significantly reduced in human thyroid tumors indicating an imbalance of oxidant/antioxidant system in TC." (PMID 40927570, 2025). "A significant lower CAT mRNA expression was reported in thyroid tumours compared to the healthy tissues." (PMID 37692064, 2023).
toxicity (2 papers, 2017 to 2022). The degree to which an agent can damage an organism. "The extract of Eucommia ulmoides bark increased the content of reduced GSH and the activity of catalase in the kidneys of cadmium-induced kidney toxicity mice and increased the SOD and GSH-Px levels in the serum of streptozotocin-induced diabetic rats." (PMID 35607702, 2022). "The activities of the SOD, CAT and GPx enzymes were significantly reduced in the PC-induced kidney toxicity group." (PMID 28134775, 2017).
trichinellosis (2 papers, 2023 to 2024). "Stimulation of antioxidant enzymes such as dismutase, peroxidase, CAT, and GSH was observed during experimental trichinellosis in mice." (PMID 38057445, 2023). "Previous studies have demonstrated alterations in specific antioxidant enzymes levels, including superoxide dismutase (SOD), catalase (CAT), glutathione-S-transferase (GST), and glutathione peroxidase (GPX), within the muscle tissues of hosts during experimental trichinellosis." (PMID 38489009, 2024).
urolithiasis (2 papers, 2012 to 2024). Stone(s) within the urinary tract. "Treatment with either emulsion or nanogel emulsion significantly elevated urolithiasis inhibitors, excreted magnesium, glutathione levels, and catalase activities." (PMID 38564033, 2024). "The findings revealed that treatment with either the emulsion or nanogel emulsion significantly prevented urolithiasis-related abnormalities, including decreased urinary excreted magnesium and non-enzymic antioxidant glutathione, as well as catalase activity." (PMID 38564033, 2024).
urticaria (2 papers, 2016 to 2025). A vascular reaction of the skin characterized by erythema and wheal formation due to localized increase of vascular permeability. "Decreased blood levels of vitamin E, catalase, and glutathione peroxidase are found in patients with physical urticarias." (PMID 27863430, 2016).
Wilson disease (2 papers, 2021 to 2025). A very rare inherited multisystemic disease presenting non-specific neurological, hepatic, psychiatric or osseo-muscular manifestations due to excessive copper deposition in the body. "This redox-stabilizing effect parallels PEN’s reported restoration of glutathione and catalase activity in Wilson’s disease." (PMID 41008627, 2025).
abortion (1 paper, 2025). the ending of pregnancy by removing a fetus or embryo before it can survive outside the uterus. "For instance, demonstrated that levels of IL5, IL6, IL1-ß, TNF-α, TLR4, and Tollip were significantly up-regulated in ewes affected with abortion than in resistant ones, while SOD and CAT gene patterns elicited an opposite trend." (PMID 40872670, 2025).
actinomycosis (1 paper, 2022). Actinomycosis is a chronic bacterial infection that commonly affects the face and neck. "Being a catalase-negative, facultatively anaerobic, gram-positive, rod-shaped organism, A. graevenitzii is isolated almost exclusively from oral or respiratory sites and may have a unique ability to cause clinical actinomycosis." (PMID 35755022, 2022).
Acute hepatitis (1 paper, 2018). Acute hepatic injury resulting from inflammation typically accompanied by increased serum alanine transaminase activity. "Thus, acute hepatitis induction with ConA led to a significant increase in MDA level (1.9 fold), GSH content (2 fold) and catalase activity (3 fold) compared to CTR." (PMID 29357846, 2018).
acute respiratory failure (1 paper, 2022). Life-threatening respiratory failure that develops rapidly. "Indeed, in our differently designed study of COVID patients admitted for acute respiratory failure and hypoxemia, admission plasma CGA concentrations instead predicted the occurrence of morbidity rather than mortality, which was better forecast by the CAT/CGA ratio." (PMID 36297613, 2022).
Adrenal insufficiency (1 paper, 2020). Insufficient production of steroid hormones (primarily cortisol) by the adrenal glands. "Adrenal insufficiency lowers basal cortisol levels of GCs, increases prooxidant biomarker (MDA), and decreases antioxidant biomarkers CAT and SOD." (PMID 33007969, 2020).
Akinesia (1 paper, 2024). Inability to initiate changes in activity or movement and to perform ordinary volitional movements rapidly and easily. "Akinesia and catatonia caused by ROT reduced the levels of endogenous antioxidants (GSH, CAT, and SOD), elevated the MDA level, and altered the levels of nitrites, neurotransmitters, and their metabolites." (PMID 38359270, 2024).
alcoholic cardiomyopathy (1 paper, 2024). A dilated cardiomyopathy which is associated with consumption of large amounts of alcohol over a period of years. "The protective role of catalase in peroxisomes is supported by studies in human fibroblasts from patients with multiple peroxisomal enzyme deficiencies and catalase deficiency, as well as in experimental animal models, such as rats with alcoholic cardiomyopathy." (PMID 39857372, 2024).
allergic rhinitis (1 paper, 2021). Inflammation of the nasal mucous membranes caused by an IgE-mediated response to external allergens. "Reduced antioxidant enzymes, such as superoxide dismutase, catalase, glutathione peroxidase, TAC, and glutathione levels, were found to be substantially lower in the blood and nasal mucosa of allergic rhinitis mice." (PMID 34836105, 2021).
androgenetic alopecia (1 paper, 2016). "Significantly decreased SOD activity but no change in catalase, glutathione peroxidase, non-protein thiols level and total antioxidant activity in erythrocytes suggest the presence of a compensatory mechanism for SOD dysfunction in red blood cells of patients with androgenetic alopecia." (PMID 27974920, 2016).
angina (1 paper, 2023). "In patients with an unstable form of angina, prooxidants (superoxide anion radical and index of lipid peroxidation) and endogenous antioxidants (catalase, superoxide dismutase and reduced glutathione) are in direct correlation with the course of ischemic disease." (PMID 37511912, 2023). "Also, lower levels of superoxide dismutase, catalase and reduced glutathione were observed as negative predictors of unstable angina." (PMID 37511912, 2023).
ankylosing spondylitis (1 paper, 2017). An autoimmune chronic inflammatory disorder characterized by inflammation in the vertebral joints of the spine and sacroiliac joints. "Our previous data also showed that CIE significantly increased the activities of catalase (CAT), SOD, and GSH-Px in ankylosing spondylitis mice." (PMID 28491105, 2017).
Aortic Rupture (1 paper, 2022). The tearing or bursting of the wall along any portion of the AORTA, such as thoracic or abdominal. "This protective effect against aortic rupture is partly attributable to the enhanced expression and activity of catalase in VSMCs." (PMID 35845076, 2022).
aortic stenosis (1 paper, 2020). Aortic valve stenosis is a aortic valve disease caused by the incomplete opening of the aortic valve. "The aortic stenosis was associated with a decrease in plasma catalase activity and in total antioxidant capacity (TAC) regardless of the type of diet, without influencing significantly the GSH/GSSG ratio." (PMID 33142857, 2020).
aortic valve calcification (1 paper, 2020). "SOD3 and catalase are downregulated with aortic valve calcification and in CAVS." (PMID 32411328, 2020).
aortic valve disease (1 paper, 2017). "Although the reason for the greater susceptibility to I/R injury of myocardium from patients with aortic valve disease is unclear, it may be that the increased myocardial catalase content reflects the body’s attempt to combat the excess oxidative stress." (PMID 28380047, 2017).